PTCH1 (patched 1)
Diseases named in the same sentence as PTCH1 in open-access papers (continued):
Sharing a sentence is not in itself a finding about the gene and the disease.
coloboma (1 paper, 2021). An abnormality in which a part of a structure in one or both eyes is missing. "Thus, whereas the extraocular features in individual 4[III:1] are likely attributed to the 16p11.2 deletion, it is unknown whether the bilateral coloboma also results from the 16p11.2 deletion or the PTCH1 missense variant inherited from the coloboma-affected index patient 4[II:2] or both." (PMID 33418956, 2021).
Coma (1 paper, 2021). The complete absence of wakefulness and consciousness, which is evident through a lack of response to any form of external stimuli. "Interestingly, we observed a significant increase in the general activity in COMA patient–derived fibroblasts compared with control cells resulting in higher basal expression levels of GLI1, GLI2, GLI3, and PTCH1." (PMID 33024317, 2021).
congenital hydrocephalus (1 paper, 2022). Hydrocephalus that is present at birth. "Molecular studies on congenital hydrocephalus show that, exome sequencing of 125 CH trios and 52 additional probands identified 3 genes with significant burden of rare damaging de novo or transmitted mutations, in addition to TRIM71, there are SMARCC1 and PTCH1." (PMID 35356930, 2022).
cutaneous squamous cell carcinoma (1 paper, 2024). "Our study focused on comprehending cutaneous squamous cell carcinoma in the Mexican population through the examination of genetic variants of the PTCH1 gene, the assessment of its mRNA’s relative expression, and the utilization of bioinformatics tools." (PMID 38534460, 2024). "While the role of PTCH1 in cutaneous squamous cell carcinoma (cSCC) has not been fully elucidated, it is well established that nearly all BCCs exhibit activated hedgehog signaling due to genetic variants in the PTCH1 gene." (PMID 38534460, 2024).
CYLD cutaneous syndrome (1 paper, 2016). "Candidates like Patched 1 (PTCH1) has been proposed earlier, but later disputed to be a potential candidate for the CYLD cutaneous syndrome." (PMID 31093340, 2016).
embryonal tumor (1 paper, 2023). "Sonidegib can improve the prognosis of patients with embryonal tumor by inhibiting PTCH1 truncating mutations." (PMID 37152984, 2023).
epidermoid cysts (1 paper, 2025). "At the molecular level, studies have revealed mutations in the PTCH1 gene, a critical regulator of the Hedgehog signaling pathway, in certain congenital forms of epidermoid cysts." (PMID 40112650, 2025).
Erythema (1 paper, 2016). Redness of the skin, caused by hyperemia of the capillaries in the lower layers of the skin. "Selection of Ptch1+/−/SKH-1 hairless mouse strain employed in this study was based on the effects of PAO on cutaneous injury (erythema and edema) in various mouse strains such as FVB, C57BL/6, SKH-1 and Ptch1+/−/SKH-136." (PMID 27725709, 2016).
hemangioblastoma (1 paper, 2016). "In contrast to these observations, we find consistent PTCH1 gains in our cohort of hemangioblastoma patients." (PMID 26768750, 2016). "In this study, we have demonstrated in two different tumor cohorts and using two different techniques for copy number alteration detection, SNP and digital PCR, that Chek2 is deleted and EGFR, PTPN11, Ptch1 amplified in majority of hemangioblastoma patients." (PMID 26768750, 2016).
Hydroureter (1 paper, 2012). The distention of the ureter with urine. "Shh and Ptch1 deletion from ureteric bud result in hydroureter and hypoplastic kidney, respectively." (PMID 22792366, 2012).
Hypertelorism (1 paper, 2025). Interpupillary distance more than 2 SD above the mean (alternatively, the appearance of an increased interpupillary distance or widely spaced eyes). "Among them, mice with a deficiency for Fgfr1, Fgfr2, Kif3a, Kras, Ptch1, Rreb1, Sos1, and Tfap2a show excessive proliferation during midfacial development, resulting in hypertelorism, suggesting that mimics of miR-383-3p and miR-6951-3p activate cell proliferation through suppression of these genes." (PMID 40787625, 2025).
invasive carcinoma (1 paper, 2016). A carcinoma that is not confined to the epithelium, and has spread to the surrounding stroma. "Kubo and colleagues found high expression of SHH, Patched 1 (PTCH1) and GLI1 in invasive carcinomas, in contrast to normal breast epithelia that do not express detectable levels of these proteins." (PMID 27548161, 2016).
keloid (1 paper, 2023). An irregularly shaped, elevated mark on the skin caused by deposits of excessive amounts of collagen during wound healing. "Furthermore, expression of the main HH target gene PTCH1 was enhanced in stem-like cells (KNS, KMS and KCS) compared with keloid fibroblasts." (PMID 38062202, 2023). "The expression of PTCH1 was enhanced in GLI1-upregulated keloid-derived stem-like cells but not in fibroblasts from keloid tissues, suggesting that the response to SHH differs between mature fibroblasts and stem-like cells." (PMID 38062202, 2023).
knee osteoarthritis (1 paper, 2021). "For example, rs76340814 (PTCH1) and rs28929474 (missense variant in SERPINA1) have stronger associations and larger effect sizes with total hip replacement (THR), total knee replacement (TKR), and total joint replacement (TJR), than with hip or knee osteoarthritis." (PMID 34450027, 2021).
leiomyosarcoma (1 paper, 2021). An uncommon, aggressive malignant smooth muscle neoplasm, usually occurring in post-menopausal women. "Inhibition of DNA methyltransferase by 5aza-dC was found to reduce PTCH1 DNA methylation, accompanied by decreased SMO and GLI1 expression and inhibition of GLI1 and GLI2 nuclear translocation in leiomyosarcoma cell lines." (PMID 34572373, 2021).
Lichen Sclerosus (1 paper, 2018). "In VSCC arising on a background of Lichen Sclerosus, the risk of local recurrence was potentiated in cases where PTCH1 was under-expressed." (PMID 30379908, 2018).
liver cancer (1 paper, 2023). An epithelial or non-epithelial malignant neoplasm that arises from the liver. "At present, some natural compounds have been found to increase Ptch1 expression, for example, the combination of epigallocatechin gallery (EGCG) and theaflavin (TF) can reduce the expression of Gli1 and Smo while increase the expression of Ptch1 in mouse liver cancer cells." (PMID 37596267, 2023).
macular holes (1 paper, 2022). A hole in the macula of the retina. "Mutations in the PTCH1 gene can lead to an abnormal intraretinal glial response that stimulates the retinal surface to proliferate and contract, creating retinal membranes, dragged vessels, and macular holes in patients with Gorlin–Goltz syndrome." (PMID 35749127, 2022).
malignant mesothelioma (1 paper, 2018). A malignant neoplasm of the pleura or peritoneum, arising from mesothelial cells. "Malignant mesotheliomas can have mutations in PTCH1, Smoothened (SMO), and SUFU genes." (PMID 29498494, 2018).
metastasis (1 paper, 2019). The spread or migration of cancer cells from one part of the body (where they first appeared) to another. "All patients with lung or liver metastasis had mutations in exon 22, or 23 of PTCH1, which is in the C-terminus of the intracellular domain of PTCH1 protein." (PMID 31704974, 2019).
metastatic prostate carcinoma (1 paper, 2004). A carcinoma that arises from the prostate gland and has spread to other anatomic sites. "To confirm this data, we found that all four available metastatic prostate cancer specimens were all positive for PTCH1 staining." (PMID 15482598, 2004). "We detected a high expression of hedgehog target genes, PTCH1 and HIP, in advanced or metastatic prostate cancers." (PMID 15482598, 2004).
multiple myeloma (1 paper, 2022). "In this study, the expression changes of PTCH1, GLI1, GLI2, Hes1, and SHH in the multiple myeloma drug-resistant cell line RPMI 8226/R were first detected." (PMID 35813864, 2022). "The results showed that the expression levels of PTCH1, GLI2, Hes1, and SHH in RPMI 8226/R were greatly increased compared with the multiple myeloma drug-sensitive cell line RPMI 8226/S, while the expression level of GLI1 was notably decreased." (PMID 35813864, 2022).
olfactory neuroblastoma (1 paper, 2024). An olfactory neuroblastoma arising in the paranasal sinus. "Olfactory neuroblastoma (ONB), another rare tumor of the epithelium in the nasal cavity, also showed activation of the Hedgehog pathway (IHC staining of PTCH1, GLI1, and GLI2), as well as inhibition by Hedgehog pathway inhibitor cyclopamine in vitro on two ONB cell lines." (PMID 38731849, 2024).
omphalocele (1 paper, 2025). Omphalocele is an embryopathy classified in the group of abdominal celosomias and is characterized by a large hernia of the abdominal wall, centered on the umbilical cord, in which the protruding viscera are protected by a sac. "Further DE gene analysis in Cluster 1 showed that Pitx2 is significantly upregulated (Log2FC 1.05, adjusted P=2.1×10−11) and Ptch1, a component of the Shh pathway that is associated with omphalocele, is significantly downregulated (Log2FC −1.86, adjusted P=9.45×10−7)." (PMID 40960281, 2025).
ovarian endometriosis (1 paper, 2021). A non-neoplastic disorder characterized by the growth of endometrial tissue in the ovaries. "We performed RWR algorithm analyses of the ceRNA network using four validated ovarian endometriosis-related genes (ESR1, SNCG, PTCH1, and MUC1) as seed nodes, prioritizing ovarian endometriosis-related lncRNAs, and we also performed permutation tests." (PMID 33584822, 2021).
pancreatitis (1 paper, 2018). Inflammation of the pancreas. "rs4437130, located upstream of the CTCN4 (contactin 4) gene, and rs62561366, located upstream of PTCH1 (patched 1), were nominally associated with thiopurine-induced pancreatitis." (PMID 29923122, 2018).
pleural mesothelioma (1 paper, 2023). A neoplasm that arises from the mesothelial cells of the pleura. "PTCH1 is a gene that encodes an effector of the HH pathway whose overexpression is associated with uncontrolled proliferation in pleural mesothelioma cell lines." (PMID 38136262, 2023). "Recently, a case report of a patient with pleural mesothelioma with a PTCH1 F1147fs mutation indicated sustained and long-lasting activity of the SMO inhibitor vismodegib." (PMID 38136262, 2023).
polydactyly (1 paper, 2016). A disease characterized by the presence of polydactyly, including syndromic and non-syndromic forms. "Prx1Cre-mediated early deletion of Ptch1, however, causes oligodactyly and is accompanied by activation of the Hh pathway, whereas late Ptch1 depletion causes polydactyly." (PMID 26959361, 2016).
prostate tumors (1 paper, 2004). "In contrast, only 22% of prostate tumors with Gleason scores 3–6 have elevated expression of PTCH1 and HIP." (PMID 15482598, 2004). "Immunohistostaining with sonic hedgehog antibodies indicate that sonic hedgehog is highly expressed in 24 of 27 advanced prostate tumors with elevated expression of PTCH1 and HIP." (PMID 15482598, 2004). "We find that high levels of hedgehog target genes, PTCH1 and hedgehog-interacting protein (HIP), are detected in over 70% of prostate tumors with Gleason scores 8–10, but in only 22% of tumors with Gleason scores 3–6." (PMID 15482598, 2004).
Renal cyst (1 paper, 2012). A fluid filled sac in the kidney. "Finally, we report the first renal mesenchymal deletion of Patched1 (Ptch1), the receptor for sonic hedgehog (Shh), which results in renal cysts demonstrating a functional role of Shh signaling pathway in renal cystogensis." (PMID 22792366, 2012).
retinoblastoma (1 paper, 2019). A malignant tumor that originates in the nuclear layer of the retina. "Analogous to retinoblastoma and other autosomal dominant forms of heritable cancer, BCCs in BCNS patients, arise through a two-hit mechanism in which “one hit” is an inherited, inactivating mutation in PTCH1, and the second hit is a somatically derived mutation in the remaining PTCH1 allele." (PMID 30858923, 2019).
Robinow syndrome (1 paper, 2011). Robinow syndrome (RS) is a rare genetic syndrome characterized by limb shortening and abnormalities of the head, face and external genitalia. "The deletion does not involve the PTCH1 gene, but instead 30 other gene,s including the ROR2 gene (MIM *602337) which causing both brachydactyly type 1 (MIM #113000) and Robinow syndrome (MIM #268310), and the immunologically active SYK gene (MIM *600085)." (PMID 21693067, 2011).
scleroderma (1 paper, 2020). Scleroderma is a rare autoimmune connective tissue disorder characterized by abnormal hardening of the skin and, sometimes, other organs. "We additionally demonstrate that the promoters of the hedgehog-associated genes GLI1 and PTCH1 are more readily accessible in scleroderma fibroblasts." (PMID 32814713, 2020). "We then evaluated how primary dermal fibroblasts from scleroderma and normal skin regulate promoter accessibility of JUN and the hedgehog-associated genes GLI1 and PTCH1 through assay of transposase accessible chromatin sequencing (ATAC-Seq) studies." (PMID 32814713, 2020).
serous ovarian cancers (1 paper, 2020). "This analysis revealed an enrichment of SHH pathway genes, including GLI1, GLI2, HHIP, PTCH1, and PTCH2, in SSTs as compared to high-grade serous ovarian cancers and other sex cord-stromal tumors." (PMID 31896750, 2020).
situ carcinoma (1 paper, 2024). "In contrast to his liver metastasis, the in situ carcinoma had a somewhat lower tumor mutational burden, lacked PD-L1/2 amplification, and had a distinct PTCH1 mutation, suggesting that the in situ BCC of his skin and the metastatic BCC of his liver were derived from different clones of cells." (PMID 39429413, 2024).
small cell lung carcinoma (1 paper, 2023). Small cell lung cancer (SCLC) is a highly aggressive malignant neoplasm, accounting for 10-15% of lung cancer cases, characterized byrapid growth, and early metastasis.
spinal chordoma (1 paper, 2019). A slow-growing malignant bone tumor arising from the remnants of the notochord and occurring in the spine. "The results of the in situ hybridization in our study were partially positive for PTCH1 and GLI1 in primary conventional cranial and spinal chordoma." (PMID 30769952, 2019).
spinal cord injury (1 paper, 2017). Penetrating and non-penetrating injuries to the spinal cord resulting from traumatic external forces (e.g., WOUNDS, GUNSHOT; WHIPLASH INJURIES; etc.). "This study aimed to investigate the effect of Patched-1 (PTC1) and PTC2 silencing in a rat model, on Hedgehog (Hh) pathway-mediated recovery from spinal cord injury (SCI)." (PMID 29244790, 2017).
squamous papilloma (1 paper, 2015). A benign epithelial neoplasm characterized by a papillary growth pattern and a proliferation of neoplastic squamous cells without morphologic evidence of malignancy. "Not surprisingly given their SKH-1 background, the chronically UVB-irradiated Ptch1+/−/SKH-1 mice also developed squamous papillomas and SCCs." (PMID 26413810, 2015).
syndromic (1 paper, 2025). "In this study, we focused on syndromic disorders caused by seven tumor suppressor genes: FH, NF1, PTCH1, RB1, STK11, and TSC1/2." (PMID 40702147, 2025).
thymoma (1 paper, 2021). A neoplasm arising from the epithelial cells of the thymus. "For patients with types A and B1/B2 thymoma (n = 9), seven gene mutations, including MTOR, BRCA1, APC, NF1, HRAS, NTRK3, and PTCH1, were detected, and each gene appeared only once in patients with non-TCs+type B3 TETs." (PMID 34307137, 2021).
uterine cancer (1 paper, 2025). Primary or metastatic malignant neoplasm involving the uterine corpus and/or the cervix. "The same variant was also seen in one healthy niece (age not known) of the index (A06‐04; daughter of A06‐02), while a second sister of the index (A06‐03) with uterine cancer was wild‐type for PTCH1." (PMID 40072281, 2025).
tumor (379 papers, 2006 to 2026). "-Basal cell carcinosarcoma with PTCH1 mutations in both epithelial and sarcomatoid primary tumour components." (PMID 40700068, 2025). "Few recurrent mutations were identified across the murine tumor samples, with the exception of mutations in Ptch1 that were detected in all samples." (PMID 40854122, 2025). "The PTCH1 gene is a tumor suppressor gene that encodes for the PTCH1 protein, a key element of this pathway acting as a ligand receptor that downregulates the signaling." (PMID 38534460, 2024). "Such Shh-dependent enhanced replication stress, resulting from increased origin firing and fork velocity and mediated by helicase loading and activation, has been implicated in the loss of the wild-type Ptch1 allele in tumor-prone GCPs." (PMID 39594660, 2024). "Functional studies show that mutant PTCH1/2 alleles had impaired tumor-suppressive activity when compared to wild-type PTCH1/2, owing to the downstream overactivation of Hh signaling." (PMID 39389955, 2024). "PTCH1 is a tumor suppressor gene encoding a large transmembrane protein that regulates the sonic hedgehog (SHH) signaling pathway." (PMID 38473071, 2024). "The tumor suppressor-gene PTCH1 encodes a transmembrane receptor protein for hedgehog family signaling molecules such as sonic hedgehog (SHH)." (PMID 39796697, 2024). "The PTCH1 gene, a tumor suppressor gene, encodes an inhibitory transmembrane protein receptor that continuously inhibits the activation of the Hedgehog (SHh) signaling pathway by inhibiting SMO receptor activity." (PMID 37533228, 2023). "One such driver for BCC development, is the activation of the hedgehog pathway with mutations of Patched1 (PTCH1) gene identified in the majority of tumours." (PMID 37013122, 2023). "PTCH1 is a tumour suppressor gene and inactivating mutations of it lead to unregulated cellular differentiation." (PMID 37013122, 2023). "Serial sequencing of circulating tumor DNA (ctDNA) showed that PTCH1 mutation and β2 microglobulin (B2M) mutations were observed in NSCLC patients with anti-PD-1 treatment." (PMID 36874015, 2023). "This study suggests that partial truncation of the PTCH1 CTD in epithelial cancers results in partial loss of PTCH1′s tumour suppressor activity through dysregulation of autophagy." (PMID 36672319, 2023). "The patched/hedgehog intracellular signaling pathway is responsible for regulating cell growth and tumor formation by inactivating mutation of protein patched homolog 1 (PTCH1) or activating mutation of Smoothened (SMOm)." (PMID 36874684, 2023). "•Extensive cell apoptosis caused by irradiation in tumor tissues from Ptch1-deficient mice over 3–6 weeks of age, leads to a significant increase of intracranial pressure in mice after the irradiation, which often causes the death of irradiated mice." (PMID 37074909, 2023). "The mutations that lead to abnormal hedgehog pathway activation and tumor formation are inactivating mutations of PTCH1 or activating mutations of SMOm." (PMID 37803407, 2023). "Since the discovery of the SHH pathway aberrates activation in cancers, the single-allele PTCH1-knockout mouse model has influenced our understanding of tumor development and is a valuable model that recaps the development of SHH-activated tumors." (PMID 36423085, 2022). "Chromosomal rearrangements resulting from PARP1 abrogation lead to a second hit in the PTCH1 allele, increasing the incidence of tumor formation." (PMID 35747808, 2022). "A common genetic mutation related to an increased BCC prevalence regards nevoid BCC syndrome with germline mutations of PTCH1, a tumour suppressor and Hh receptor." (PMID 36291078, 2022). "All the 6 patients with a PTCH1 mutation had an objective tumor response and some of those responses were prolonged, especially when associated with other treatment." (PMID 34409296, 2021).